RAC2 (Rac family small GTPase 2)
Diseases named in the same sentence as RAC2 in open-access papers (continued):
Sharing a sentence is not in itself a finding about the gene and the disease.
endometrial cancer (2 papers, 2023 to 2025). Primary or metastatic malignant neoplasm involving the endometrium (mucous membrane that lines the endometrial cavity). "Compared to normal tissues, the RAC2 mutation rate was higher in patients with skin melanoma, uterine sarcoma, and endometrial cancer." (PMID 37214785, 2023).
neutrophil immunodeficiency syndrome (2 papers, 2014 to 2018). "Three patients with mutations in Rac2 have been identified that suffer from a neutrophil immunodeficiency syndrome." (PMID 25165726, 2014). "Mutations within RAC2 are associated with neutrophil immunodeficiency syndrome." (PMID 29426059, 2018).
Obesity (2 papers, 2020 to 2023). Accumulation of substantial excess body fat. "Last, also the candidate regulators BIN2 and RAC2 have been associated with obesity and metabolic syndrome." (PMID 31688915, 2020). "In summary, in this study, six hub genes, including Mki67, Rac2, Itgb2, Emr1, Tyrobp and Csf1r were identified which could be used as therapeutic biomarkers for obesity." (PMID 36654490, 2023).
pancreatic cancer (2 papers, 2019 to 2023). "S-nitrosylated proteins in pancreatic cancer pathway identified in this study also include Rac1, Rac2, CDC42, STAT1, and RB, which are all important regulators of pancreatic cancer cells." (PMID 31801946, 2019).
periodontitis (2 papers, 2021 to 2023). An acute or chronic inflammatory process that affects the tissues that surround and support the teeth. "RAC2 and PTPRC were significantly increased in the periodontitis (p<0.005) and periodontitis patients with T2DM group (p <0.005) compared with the healthy control group." (PMID 35145474, 2021).
primary immunodeficiencies (2 papers, 2021 to 2024). "Impaired immune responses have been observed in primary immunodeficiencies associated with disrupted regulation of actin dynamics, such as Wiskott-Aldrich Syndrome (WASP), Coronin1A, Rac2, and ARHGEF1." (PMID 34232960, 2021).
Pseudomonas infection (2 papers, 2017 to 2020). Infections with bacteria of the genus pseudomonas. "Therefore, the increase in susceptibility to Pseudomonas infection we observed in c3a.1−/− larvae expressing wild-type rac2 is likely predominantly due to a neutrophil-intrinsic function of C3, possibly due to the reduction in numbers of neutrophils found at the infection site." (PMID 32973200, 2020).
psoriasis (2 papers, 2021 to 2025). An autoimmune condition characterized by red, well-delineated plaques with silvery scales that are usually on the extensor surfaces and scalp. "Evans syndrome and psoriasis were among the most common autoimmune clinical presentations in the RAC2 GTPase group compared to the CDC42 GTPase group." (PMID 40860338, 2025). "Our sequencing results demonstrated the downregulation of Rac2 in skin lesions of IMQ-induced psoriasis-like mice by TDGs." (PMID 33995034, 2021). "The mechanisms of TDG treatment for psoriasis include the upregulation of metabolic signaling pathways, downregulation of immune and inflammatory pathways, and a decrease in Rac2 and Arhgdib genes." (PMID 33995034, 2021). "Next, based on the protein-protein interaction analysis, we found that the skin protein expression of Arhgdib (had the highest combined scores of Rac2) in IMQ-induced psoriasis-like mice was significantly downregulated." (PMID 33995034, 2021). "To further explore the feasible mechanism by which TDGs regulate Rac2 in psoriasis, we conducted a protein-protein interaction analysis using the Search Tool for the Retrieval of Interaction Gene/Proteins (String) database based on our sequencing results." (PMID 33995034, 2021). "Hence, we speculate that TDGs may reduce Rac2 and Arhgdib and, consequently, decrease KC proliferation and migration to relieve psoriasis." (PMID 33995034, 2021).
renal carcinoma (2 papers, 2021 to 2024). A carcinoma arising from the epithelium of the renal parenchyma or the renal pelvis. "Importantly, our data provided evidence for the first time from NEDD4L CKO mice and renal cancer Caki-1 cells supporting RAC2 as a novel ubiquitylation target of NEDD4L in ccRCC." (PMID 39596003, 2024). "In NEDD4L CKO mice and ccRCC tissues, NEDD4L expression was inversely correlated with RAC2 expression, and NEDD4L directly reduced RAC2 protein levels, suggesting that aberrant NEDD4L expression may be a novel mechanism underlying RAC2 upregulation in renal cancer." (PMID 39596003, 2024).
Sepsis (2 papers, 2023 to 2025). Sepsis is defined as life-threatening organ dysfunction caused by a dysregulated host response to infection. "Severe systemic infections including septicemia, and disseminated intravascular coagulation emerged as the predominant infectious complications of CDC42 GTPase patients compared to the RAC2 GTPase group." (PMID 40860338, 2025).
staphylococcus aureus infection (2 papers, 2022 to 2023). An infectious process in which the bacteria Staphylococcus aureus is present. "Notably, 3 genes (NCF2, RAC2, and MMP9) were involved in Staphylococcus aureus infection, the most prevalent etiology of osteomyelitis in diabetic foot ulcer infections." (PMID 37904457, 2023).
Wiskott-Aldrich syndrome (2 papers, 2017 to 2021). Wiskott-Aldrich syndrome (WAS) is a primary immunodeficiency disease characterized by microthrombocytopenia, eczema, infections and an increased risk for autoimmune manifestations and malignancies. "Moreover, the majority of these genes are preferentially expressed in the hematopoietic lineage and at least three of them, Was (Wiskott Aldrich syndrome), Btk (Bruton’s tyrosine kinase) and Rac2, when mutated in humans, give rise to severe hematopoietic deficiencies." (PMID 28663935, 2017).
actinopathies (1 paper, 2025). "Defects in both CDC42 and RAC2 GTPases have been linked with actinopathies but associated with distinct immune disorders." (PMID 40860338, 2025). "Majority of patients from MENA-IEI registry with actinopathies have defects in CDC42 GTPase and RAC2 GTPase pathways." (PMID 40860338, 2025).
Artemis deficiency (1 paper, 2024). "Sixpatients had ADA deficiency, 3 had IL2RG deficiency, 3 had CD3 Delta deficiency, 2 had Artemis deficiency (affecting DCLRE1C), and 1 each had variants impacting NHEJ1, TRAC, RAC2, and RMRP." (PMID 39062699, 2024).
arteriosclerosis (1 paper, 2023). A vascular disorder characterized by thickening and hardening of the walls of the arteries. "Several studies have confirmed that RAC2 affects the development of arteriosclerosis by regulating the activity of macrophages." (PMID 37735234, 2023).
aspergillosis (1 paper, 2024). Aspergillosis is an infection, growth, or allergic response caused by the Aspergillus fungus. "The increased risk of aspergillosis in patients who have been treated with BTKi is likely a result of the combined defects in p40phox and RAC2 activation caused by BTKi treatment, which may synergistically heighten susceptibility relative to each defect alone." (PMID 38696257, 2024). "It is important to note that aspergillosis has not been observed in the limited number of patients reported with inherited p40phox and RAC2 deficiencies." (PMID 38696257, 2024).
autoimmune thyroid disease (1 paper, 2022). Inflammatory disease of the thyroid gland due to autoimmune responses leading to lymphocytic infiltration of the gland. "Genomes associated with autoimmune thyroid disease, allograft rejection, and cell adhesion molecule signaling were differentially enriched in the RAC2 high-expression phenotype." (PMID 36212434, 2022). "In addition, GSEA analysis showed that DIRAS3, GPR171, and RAC2 are involved in signaling pathways such as ECM–receptor interaction, complement and cohesion cascades, adhesion plaques, allograft rejection, autoimmune thyroid disease, graft-versus-host disease, and cell adhesion molecules." (PMID 36212434, 2022).
bladder cancer (1 paper, 2025). "Existing research indicates that RAC3 can influence autophagy in bladder cancer cells, but whether RAC2 exhibits a similar mechanism in other malignancies requires further investigation." (PMID 40072059, 2025).
cardiomyopathy (1 paper, 2021). A disease of the heart muscle or myocardium proper. "The Rac2/cofilin pathway was found to play a crucial role in the sarcomere morphology and Z-line arrangement disarray induced by the RVOT bigeminy VPC, which may underlie VPC-induced cardiomyopathy." (PMID 34681906, 2021).
chronic lymphocytic leukemia (1 paper, 2025). "This enhanced RAC2-PLCγ2 interaction was also observed in chronic lymphocytic leukemia cells from patients with treatment-resistant or progressive disease on BTK inhibitor treatment." (PMID 40072059, 2025). "However, in chronic lymphocytic leukemia (CLL) cells with NOTCH1 mutations, RAC2 appears to function downstream of NOTCH signaling as inhibition of the NOTCH pathway with PF-03084014 leads to downregulation of RAC2 along with other genes involved in invasion and chemotaxis." (PMID 40072059, 2025).
common variable immunodeficiency (1 paper, 2021). "Study of a loss-of-function mutation in RAC2 in patients suffering from common variable immunodeficiency revealed impaired chemotaxis of RAC2-deficient neutrophils." (PMID 34867982, 2021).
cutaneous melanoma (1 paper, 2023). A primary melanoma arising from atypical melanocytes in the skin. "RAC2 showed the highest change frequency (P > 3%) in cutaneous melanomas with “mutation” and “amplification” as the dominant types." (PMID 37214785, 2023).
cystic fibrosis (1 paper, 2024). Autosomal recessive disorder caused by pathogenic variants in the CFTR gene (cystic fibrosis transmembrane conductance regulator), which encodes a chloride and bicarbonate channel expressed in epithelial cells, and follow the diagnosis criteria. "In contrast, increased primary granule release by neutrophils of patients with cystic fibrosis most likely involves increased Rac2 activation." (PMID 39493757, 2024).
diabetic nephropathy (1 paper, 2021). "Hub genes (FPR3, C3AR1, CD14, ITGB2, RAC2 and ITGAM) related to iron death in diabetic nephropathy were obtained through gene expression differential analysis between different subtypes." (PMID 34735495, 2021). "Finally six Hub genes related to iron death in diabetic nephropathy were obtained, including FPR3, C3AR1, CD14, ITGB2, RAC2 and ITGAM." (PMID 34735495, 2021).
E. coli infection (1 paper, 2024). "Immunohistochemistry identified that E. coli infection-induced upregulation of Sca-1 expression on the surface of marrow precursor cells tightly colocalized with cell membrane-recruited Rac2 in wild-type mice." (PMID 38665923, 2024).
eczema (1 paper, 2025). "Moreover, allergic presentations, particularly eczema (72.7%) were significantly more prevalent in the defective CDC42 pathway rather than RAC2 pathway." (PMID 40860338, 2025).
fibrosis (1 paper, 2014). the formation of excess fibrous connective tissue in an organ or tissue in a reparative or reactive process. "Although a different model was used in our study, our findings show an additional role for Rac2 in lung physiology and mortality associated with fibrosis, which has not been reported before." (PMID 24970330, 2014).
glaucoma (1 paper, 2008). Increased pressure in the eyeball due to obstruction of the outflow of aqueous humor. "In the current study, using microarray analysis, we identified a number of genes (for example, MYLK, TGFBR2, VCAN, and RAC2) whose expression may underlie higher susceptibility of astrocytes of AA individuals to elevated IOP and that may be relevant to reactive astrocyte responses in glaucoma." (PMID 18613964, 2008).
Granuloma (1 paper, 2026). A compact, organized collection of mature mononuclear phagocytes, which may be but is not necessarily accompanied by accessory features such as necrosis. "Pharmacological and genetic interventions revealed a crucial role for PI3Kγ/δ and the Rac2 signaling axis in neutrophil-mediated support of mycobacterial survival in granulomas." (PMID 41564181, 2026).
hyperlipidemia (1 paper, 2021). "Given the background of the ApoE-deficient mouse model of hyperlipidemia, Rac2 deletion resulted in elevated circulating IL-1β in blood plasma from mice on a cholesterol-supplemented high-fat diet." (PMID 34831028, 2021). "Moreover, outside of Rac2 deletion leading to progressive atherosclerotic calcification, the relative impact of this Rac1–IL-1β signaling axis in the natural progression of atherosclerosis and/or atherosclerotic calcification in the context of hyperlipidemia remains unclear." (PMID 34831028, 2021).
infectious colitis (1 paper, 2013). A viral or bacterial infectious process affecting the large intestine. "Collectively, our findings demonstrate that Rac2−/− mice develop more severe disease when subjected to a C. rodentium-induced model of infectious colitis, and suggest that impaired Rac2 function may promote the development of IBD in humans." (PMID 23613889, 2013).
intellectual disabilities (1 paper, 2024). "The NEDD4L/RAC2/WASF1 may be a novel pathway associated with NEDD4L-related neurodevelopmental and intellectual disabilities." (PMID 39596003, 2024).
ischemia (1 paper, 2023). A hypoperfusion of the BLOOD through an organ or tissue caused by a PATHOLOGIC CONSTRICTION or obstruction of its BLOOD VESSELS, or an absence of BLOOD CIRCULATION. "It has also been reported in a hepatic ischemia/reperfusion injury model that blocking TLR9 can downregulate the expression of PAD4 and Rac2, which are essential for NETs formation." (PMID 37365190, 2023).
lentivirus infection (1 paper, 2019). Virus diseases caused by the Lentivirus genus. "Then, 92-shRAC2 and OCM-RAC2, with RAC2 knock-down in 92-1 cells and radiation-inducible RAC2 overexpression in OCM-1 cells respectively, as well as their negative control cell lines (92-NC and OCM-NC) were established by corresponding lentivirus infection and puromycin selection." (PMID 31281584, 2019).
lung adenocarcinoma (1 paper, 2016). A carcinoma that arises from the lung and is characterized by the presence of malignant glandular epithelial cells. "Next, we compared the expression of RAC2 and CDA mRNAs between DMSO and U0126 treatments in the three KRAS-mutant lung adenocarcinoma cell lines." (PMID 27846317, 2016).
microcytic anemia (1 paper, 2013). Anemia in which the red blood cell volume is decreased. "Kalfa and colleagues previously found that mice deficient in Rac1 and Rac2 (Rac1−/−Rac2−/− mice) exhibited mild microcytic anemia with significant anisocytosis, poikilocytosis, polychromasia, and increased hypochromic cells, target cells, and fragmented erythrocytes." (PMID 23424621, 2013). "In mice, conditional disruption of Rac1 and Rac2 results in microcytic anemia characterized by gaps in the actin membrane skeleton, irregularity of the spectrin scaffold, decreased deformability, and decreased representation of essential skeletal proteins including α- and β- spectrin and adducin." (PMID 23424621, 2013).
multiple myeloma (1 paper, 2022). "A previous microarray-based study found that RAC2, Rac family small GTPase 2, is significantly upregulated in multiple myeloma as compared with MGUS." (PMID 36969740, 2022). "In summary, previous studies indicated RAC2 and PSMB9 are associated with disease development from MGUS to multiple myeloma and our analysis suggested that they might also be related to multiple myeloma progression." (PMID 36969740, 2022). "RAC2 and PSMB9 have been revealed to be associated with disease development from MGUS to multiple myeloma and our analysis suggested that they might also be related to multiple myeloma rapid progression, supported by both scRNA-seq and CITE-seq." (PMID 36969740, 2022). "We also found that RAC2 and PSMB9 are upregulated in NK cells in FPs relative to NPs at transcriptional level, which could potentially serve as multiple myeloma progression markers." (PMID 36969740, 2022).
non-alcoholic steatohepatitis (1 paper, 2017). "Moreover, in a data set downloaded from the GEO database (accession code GSE63067), gene expression of Tlr4, Nox2, Rac1 and Rac2 was remarkably increased in patients with non-alcoholic steatohepatitis compared with heathy controls." (PMID 29269727, 2017).
oral lichen planus (1 paper, 2023). Oral lichen planus is a chronic inflammatory oral condition of unknown aetiology characterized by T-cell-mediated chronic immune response and abnormal epithelial keratinization cycle. "The association of RhoGDI2 and Rac2 was also reported in a signaling pathway that is implicated in the pathogenesis of oral lichen planus (OLP), a chronic inflammatory and immune-mediated disease affecting skin, nail, hair and mucous membranes." (PMID 36835422, 2023).
parasitic infection (1 paper, 2014). "We conclude that Rac2 provides the signaling specificity to drive the M2 macrophage phenotype under conditions of inflammation where macrophages are interacting with the provisional extracellular matrix and immunoregulation is key, e.g. parasitic infection." (PMID 24770346, 2014).
polyarticular JIA (1 paper, 2018). "The strongest non‐HLA association for RF‐positive polyarticular JIA was rs9610687, which lies upstream of the RAC2 gene." (PMID 29426059, 2018).
prion disease (1 paper, 2025). A transmissible disease that is caused by a protein that is able to induce abnormal folding of normal cellular proteins, leading to characteristic spongiform brain changes, which are associated with neuronal loss without an inflammatory response. "We compare down/up-regulated proteins from C− versus 5RINM with altered proteins related to chemical carcinogenesis, reactive oxygen species (e.g., down-regulated P48962/Slc25a4, P51881/Slc25a5, Q9CQQ7/Atp5f1, or P12787/Cox5a), and prion disease (e.g., down-regulated Q05144/Rac2)." (PMID 40006055, 2025).
progressive multifocal leukoencephalopathy (1 paper, 2022). Progressive multifocal leukoencephalopathy (PML) is a neurological disorder that damages the myelin that covers and protects nerves in the white matter of the brain. "We present the first reported case of progressive multifocal leukoencephalopathy due to a mutation in the RAC2 gene." (PMID 35689244, 2022).
renal cell carcinoma (1 paper, 2024). "RAC2 is the first identified target of NEDD4L in renal cell carcinoma." (PMID 39596003, 2024).
renal fibrosis (1 paper, 2021). A final common manifestation of a wide variety of chronic kidney diseases characterized by glomerulosclerosis and tubulointerstitial fibrosis. "Among these, RAC2 has been shown to interact with nitric oxide synthase 2A and correlate with renal fibrosis." (PMID 34777334, 2021).
retinal vein occlusion (1 paper, 2025). An occlusion of the retinal vein. "In the context of retinal hypoxia as seen in diseases like DR, retinal vein occlusion (RVO), and AMD, RAC1 and RAC2 are implicated through several mechanistically relevant pathways." (PMID 40906190, 2025).
T-cell leukemia (1 paper, 2017). A malignant disease of the T-lymphocytes in the bone marrow, thymus, and/or blood. "A study also showed that Vav1 plays a unique role in T-cell leukemia survival by selectively triggering the Rac2-Akt axis and elevating the expression of anti-apoptotic Bcl-2." (PMID 28029655, 2017).
temporal lobe epilepsy (1 paper, 2024). A localization-related (focal) form of epilepsy characterized by recurrent seizures that arise from foci within the temporal lobe, most commonly from its mesial aspect. "Upregulation of leukocyte NCF2, RAC2 and HMOX1 expression in this study is predictive of low temporal lobe epilepsy seizure frequency, while downregulation of these genes predicts high seizure frequency." (PMID 38166692, 2024). "NCF2, RAC2 and HMOX1 activity all promote epileptogenicity through mitochondrial oxidative stress, neuronal lipid peroxidation, and neuronal and glial toxicity, all of which are consistent with the redox imbalance hypothesis of temporal lobe epilepsy." (PMID 38166692, 2024).